ATG7 (autophagy related 7)
Diseases named in the same sentence as ATG7 in open-access papers (continued):
Sharing a sentence is not in itself a finding about the gene and the disease.
gastric cancer (17 papers, 2017 to 2025). A primary or metastatic malignant neoplasm involving the stomach. "First, using the GEPIA database, we found that ATG7 is highly expressed in gastric cancer, and that patients with high ATG7 expression have a lower overall survival (OS) compared to those with low expression." (PMID 39464718, 2024). "The results showed that ATG7 expression levels were significantly upregulated in the three gastric cancer cell lines (HGC27, MKN28, AGS) compared to the normal gastric mucosal epithelial cell line GES-1 (*p<0.05, **p<0.01, ***p<0.001)." (PMID 39464718, 2024). "Subsequently, to explore the specific mechanisms of microRNA-582-3p in gastric cancer, we verified the downstream target of microRNA-582-3p, ATG7, using dual-luciferase reporter assays and examined the effect of ATG7 on gastric cancer cell functions." (PMID 39464718, 2024). "Next, we further explored the impact of ATG7 on the biological functions of gastric cancer cell lines." (PMID 39464718, 2024). "Knockdown of ATG7 suppressed the malignant biological functions of gastric cancer cells and enhanced their sensitivity to oxaliplatin." (PMID 39464718, 2024). "To further demonstrate that MiR-582-5p exerts its effects by targeting ATG7, we conducted rescue experiments by co-overexpressing ATG7 and MiR-582-5p in gastric cancer cell lines." (PMID 39464718, 2024). "MiR-582-5p promotes invasion and metastasis of gastric cancer cells by negatively regulating ATG7 expression." (PMID 39464718, 2024). "miR-582-5p inhibits the expression of ATG7 in gastric cancer cells, thereby suppressing autophagy levels and influencing proliferation, migration, invasion, and resistance to oxaliplatin in gastric cancer cells." (PMID 39464718, 2024). "Transwell assays further validated that co-overexpression of ATG7 reversed the phenotypic changes induced by MiR-582-5p overexpression in gastric cancer cells, including their sensitivity to oxaliplatin." (PMID 39464718, 2024). "In the future, we hope that further functional analysis of the rs4684787 in ATG7 will lead to pathological findings and the development of new therapeutic GMA drugs to reduce gastric cancer risk." (PMID 38276136, 2024). "A recent study uncovered the promotional impact of circRACGAP1 on gastric cancer cell sensitivity to apatinib through the modulation of the miR-3657/ATG7 axis." (PMID 33782039, 2021). "Gastric cancer tissue-derived exosomes also induced higher ATG7 and BECN1 expression and NF-κB activation in neutrophils than non-cancerous tissue-derived exosomes." (PMID 30292233, 2018). "Recombinant HMGB1-treated neutrophils promoted the migration of gastric cancer cells and increased the expression of ATG7 and BECN1 genes in neutrophils." (PMID 30292233, 2018). "To further investigate the mechanism by which MiR-582-5p affects gastric cancer cell biological functions and sensitivity to oxaliplatin, we assessed the expression of ATG7 at both the RNA and protein levels following MiR-582-5p overexpression and knockdown using q-PCR and western blotting." (PMID 39464718, 2024). "By examining ATG7 expression in gastric cancer cells, we observed high levels of ATG7 expression." (PMID 39464718, 2024). "Our study confirms that microRNA-582-3p acts as a tumor suppressor in gastric cancer cells, and its role may be mediated through the regulation of ATG7 expression levels." (PMID 39464718, 2024). "To investigate whether its overexpression affects the biological functions of gastric cancer, we designed two siRNAs targeting ATG7 and established transiently transfected gastric cancer cell lines with reduced ATG7 expression." (PMID 39464718, 2024). "In addition, HMGB1 antagonist reversed gastric cancer tissue-derived exosomes-induced increases of ATG7 and BECN1 expression in neutrophils." (PMID 30292233, 2018).
gastric cancer (continued). "Additionally, using Transwell and CCK8 assays, we evaluated the impact of ATG7 knockdown on gastric cancer cell resistance to oxaliplatin, revealing suppressed proliferation, invasion, migration, and oxaliplatin resistance after ATG7 knockdown (*P < 0.05, **P < 0.01, ***P < 0.001)." (PMID 39464718, 2024). "Moreover, ATG7 is overexpressed in gastric cancer cells; knockdown of ATG7 inhibits the biological functions of gastric cancer cells and increases their sensitivity to oxaliplatin, whereas overexpression of ATG7 reverses the inhibitory effect of miR-582-5p on gastric cancer." (PMID 39464718, 2024). "Furthermore, we further confirmed that miR-582-5p suppresses cancer cell autophagy levels and epithelial-mesenchymal transition (EMT) by targeting ATG7 expression, thereby influencing the malignant biological functions and oxaliplatin resistance of gastric cancer cells." (PMID 39464718, 2024). "Additionally, we observed high expression of ATG7 in gastric cancer tissues and cells." (PMID 39464718, 2024). "Therefore, we suggest that Micro-582-5p may enhance resistance of gastric cancer cells to oxaliplatin by inhibiting ATG7." (PMID 39464718, 2024). "TRIM65 knockdown inhibits autophagy of A549/DDP cells through the miR-138-5P/ATG7 pathway, whereas TRIM14 promotes autophagy in gastric cancer cells by activating the AMPK pathway." (PMID 36587218, 2022). "It has been previously reported that ATG7 and ATG9 key regulatory factors affect the prognosis and progression of gastric cancer." (PMID 31988807, 2020). "D. QRT-PCR analyses of ATG7 and BECN1 gene expression in gastric cancer cell-derived exosomes-treated neutrophils." (PMID 30292233, 2018). "Moreover, correlation analysis showed that TOB1 was positively correlated with the expression of ATG3 and ATG7 in gastric cancer but not in normal gastric tissue." (PMID 35186488, 2022). "However, whether miR-582-5p affects gastric cancer cell biological functions and sensitivity to oxaliplatin through targeting ATG7 has not been reported." (PMID 39464718, 2024). "The expression level of TOB1 was positively correlated with the expression levels of ATG3 (R = 0.32, ***P = 2 × e−11) and ATG7 (R = 0.23, ***P = 1.7 × e−06) in gastric cancer tissues but not in normal gastric tissue (ATG3, R = 0.027, P = 0.7; ATG7, R = 0.033, P = 0.64)." (PMID 35186488, 2022).
glioblastoma (17 papers, 2017 to 2025). The most malignant astrocytic tumor (WHO grade IV). "Inhibitors or silencing ATG7 increases Quercetin-induced ROS and leads to apoptosis in glioblastoma cells." (PMID 35883843, 2022). "In the KRAS-driven glioblastoma mouse model, autophagy blocked Atg7, Atg13, or Ulk1 by shRNA; inhibited the occurrence and growth of tumors; and extended the survival of mice." (PMID 33194668, 2020). "Downregulating the autophagy players DRAM1, SQSTM1 and ATG7 impaired the capacity of patient-derived, mesenchymal-like GSCs to invade using a transwell cell culture system, supporting a role for autophagy in glioblastoma invasion." (PMID 32873152, 2020). "This was achieved using the RCAS/TVA GEMM of glioblastoma induced by overexpressing KRASG12D in a Cdkn2a−/− background where autophagy was disrupted by genetic knockdown of Atg7, Atg13 or Ulk1 in tumour cells." (PMID 32873152, 2020). "A similar approach was used on T98G glioblastoma cells to demonstrate that miR-17 negatively regulated ATG7 expression, thus contributing to an overall downregulation of the autophagic process." (PMID 28208686, 2017). "Similarly, MIR17 suppresses the expression of ATG7 (autophagy-related 7) in human glioblastoma T98G cells." (PMID 39684286, 2024). "We investigated the requirement of functional autophagy machinery by utilizing pharmacological inhibitors or CRISPR-Cas9 knockout (KO) of autophagy-related genes -5 and -7 (ATG5 and ATG7) in glioblastoma cells and monitored changes in autophagic flux after temozolomide and/or bortezomib treatments." (PMID 36619857, 2022). "Similarly, autophagy gene expression profiles in publicly available glioblastoma datasets show that the mesenchymal subclass exhibited increased ATG gene transcription, including ATG7, LC3B, LC3C, ATG16L1 and SQSTM1 (which encodes p62)." (PMID 32873152, 2020). "The miRNA could modulate autophagy by negatively regulating ATG7 expression in human glioblastoma cells." (PMID 28459042, 2017). "Moreover, miR-137, which takes part in neuronal maturation and neurogenesis, suppressed starvation-induced autophagy by targeting ATG7 in glioblastoma cells." (PMID 28459042, 2017). "Likewise, as compared to control microglia, the Atg7-deficient microglia did not display any difference in the glioblastoma-induced tumor-supportive function." (PMID 34082793, 2021). "Silencing autophagy-related genes Atg5 and Atg7 enhances apoptosis, suggesting that autophagy may act as a protective mechanism in CB2R-expressing glioblastoma cells." (PMID 40483537, 2025). "A study comparing the effects of curcumin and solid lipid curcumin particles on autophagy and mitophagy in glioblastoma multiforme cells showed that SLCPs demonstrated superior induction of autophagy markers (Atg5, Atg7, Beclin-1, and LC3A/B) compared to Cur in U-87MG, GL261, and F98 GBM cell lines." (PMID 40227413, 2025). "Deletion of TSC2 in the glioblastoma GL261 cells enhanced their sensitivity to IXZ, while deletion of ATG7 did not, similar to MM." (PMID 36400754, 2022).
Hepatic steatosis (17 papers, 2015 to 2025). Steatosis is a term used to denote lipid accumulation within hepatocytes. "Altogether, T cell-specific Atg7 deficiency hampered WTD-induced hepatic steatosis and dyslipidemia despite successful viral transduction with rAAV2/8-D377Y-mPCSK9." (PMID 30619297, 2018). "Here, we show that atherosclerosis development is severely hampered in mice with T cell-specific Atg7 deficiency and that this is associated with decreased hepatic steatosis and by decreased frequencies of CD4+, CD8+ T cells, and natural killer T (NKT) cells." (PMID 30619297, 2018). "In conclusion, T cell-specific Atg7 deficiency decreased the degree of diet-induced hepatic steatosis and atherosclerosis due to a decrease in numbers of CD4+, CD8+, and NKT cells." (PMID 30619297, 2018). "Liver-specific Vps34 knockout mice developed hepatomegaly and hepatic steatosis, which is highly similar to the phenotype observed in the autophagy-deficient Atg7−/− and Atg5−/− livers." (PMID 26589724, 2015). "We speculate that the deficiency of Atg7 prevents the storage of adipose-derived fatty acids in lipid droplets, resulting in resistance to hepatic steatosis." (PMID 39798881, 2025). "Atg7-deficient mice have exacerbated hepatic steatosis during fasting." (PMID 39798881, 2025). "Taken together, T cell-specific deficiency of Atg7 resulted in a decrease in hepatic steatosis and limited inflammatory potency in the (naïve) T cell compartment in peripheral lymphoid tissues, which was associated with a strong reduction in experimental atherosclerosis." (PMID 30619297, 2018). "To our surprise, we found that global loss of Atg7 during exposure to PEG-asparaginase impaired transcriptional execution of the ISR in the liver and protected mice from weight loss and liver steatosis." (PMID 39798881, 2025). "Loss of Atg7 in the liver also protects mice from PEG-asparaginase-induced weight loss, hepatic steatosis, and blunts the transcriptional execution of the ISR in the liver." (PMID 39798881, 2025). "On the opposite, enhancing autophagy by Atg7 overexpression improved hepatic steatosis and insulin resistance in ob/ob mice and mice fed a HFD." (PMID 34141709, 2021). "For instance, the overexpression of Atg7 in the liver is sufficient to prevent hepatic steatosis in ob/ob mice." (PMID 34366846, 2021). "In fact, it was already reported that trehalose improved metabolic parameters and prevented hepatic steatosis in obese Atg7+/− mice, through attenuation of autophagy." (PMID 29241092, 2018). "Given that Atg7-deficient mice and humans with genetic polymorphisms in the Atg7 gene develop fatty liver disease, we hypothesized the autophagic degradation of hepatic lipids may mitigate PEG-asparaginase-induced hepatic steatosis." (PMID 39798881, 2025). "Contrary to our hypothesis, we found that Atg7 is a contributor to PEG-asparaginase-induced hepatic steatosis." (PMID 39798881, 2025). "Moreover, liver-specific deletion of Atg7, whose protein stimulates phagophore expansion, increases hepatic fat content in mice, mimicking the human condition of hepatic steatosis." (PMID 38978979, 2024). "For example, mice fed high-fat diets and in which an autophagy-related gene (Atg7) was knocked out showed a marked increase in hepatic triglycerides and cholesterol content, indicating that defects in autophagy may promote hepatic steatosis." (PMID 39519065, 2024). "Furthermore, enhancing autophagy by overexpressing Atg7, improved hepatic steatosis in ob/ob mice and mice fed a HFD." (PMID 34141709, 2021). "Since hepatic steatosis was decreased upon T cell-specific deletion of Atg7, we hypothesized that this was due to a reduction in the numbers and profile of cytokine secretion of CD4+ and CD8+ T cells in the livers of Lck-Cre Atg7f/f mice." (PMID 30619297, 2018).
Hepatic steatosis (continued). "In conclusion, although Atg7 deficiency resulted in a relative increase in T cells which produce inflammatory cytokines, the decrease in CD4+ and CD8+ T cells in the liver likely impairs the development of hepatic steatosis in Lck-Cre Atg7f/f mice." (PMID 30619297, 2018). "Furthermore, Atg7 knockout in liver led to accelerated development of liver steatosis." (PMID 33804819, 2021). "Thus, T cell-specific Atg7 deficiency not only diminished the CD4+ and CD8+ T cell populations but also severely reduced the percentage of hepatic NKT cells, which may have contributed to impaired hepatic steatosis development as suggested by literature." (PMID 30619297, 2018). "Herein, MG increased ATG5-12, ATG7, Beclin1, ULK1, and LC3-II/I ratio and decreased p62/SQSTM1 and p-mTOR in the liver of Tylo-injected rats and PA-stimulated HepG2 cells, suggesting that MG might promote the formation of autophagic flux to alleviate hepatic steatosis." (PMID 32992548, 2020).
Sepsis (17 papers, 2014 to 2025). Sepsis is defined as life-threatening organ dysfunction caused by a dysregulated host response to infection. "A further study proved that in Pseudomonas aeruginosa–induced sepsis, flagellin is an effective activator of the inflammasome, and loss of Atg7 led to increased pyroptosis." (PMID 35572571, 2022). "In a P. aeruginosa-induced sepsis mice model, Atg7 deficiency significantly intensifies inflammasome activation and provokes pyroptosis in AMs, leading to impaired pathogen clearance and aggravated lung injury." (PMID 30717487, 2019). "Secondly, elimination of the autophagy protein ATG7 with the use of T cell-specific Atg7-knockout mice resulted in an increase in sepsis-induced mortality and a loss of CD4+ and CD8+ T cells to apoptosis." (PMID 25029098, 2014). "In a CLP model of sepsis induction, electron microscopy revealed a reduction in autophagic vesicles within the spleens of T-cell-specific Atg7-deficient mice post-CLP, which presented increased mortality rates due to sepsis, increased T-cell apoptosis, and depletion of CD4+ and CD8+ T cells." (PMID 40153575, 2025). "In summary, sepsis-associated plasma EVs may induce ALI through targeted inhibition of ATG7 and autophagy by miR-210-3p." (PMID 34321587, 2021). "Suppressed cytokine production of Th1/Th2/Th17 by Atg7-deficient CD4+ T cells after sepsis may therefore be partially mediated by insufficient energy secondary to autophagy deficiency." (PMID 25029098, 2014). "Hence, Atg7 deletion may contribute to enhanced pyroptosis, and the molecular mechanism underlying bacterial infection and sepsis progression should be further studied." (PMID 29706799, 2018). "In a rat model of sepsis, ghrelin administration was found to significantly upregulate the autophagy markers LC3, ATG7, and beclin-1 in small intestinal epithelial cells during early sepsis." (PMID 38275675, 2024). "Although Beclin1, Atg7, and Atg12 in the Sepsis group were all slightly higher than the SFP group (p < 0.05), Unc-51-like autophagy activating kinase (Ulk1), Atg5, Atg8l, and Lamp2 were not different." (PMID 37106730, 2023). "Consistent with a role in regulating inflammatory responses, inflammasome activity is enhanced in Atg7 KO mouse infected with Pseduomonas aeruginosa, impairing pathogen clearance, thus implicating ATG7 in sepsis pathogenesis." (PMID 34725936, 2021). "Taken together, the key findings of our study highlight that the plasma EV-mediated delivery of miR-210-3p targets ATG7 to regulate autophagy and inflammatory activation in sepsis-induced ALI." (PMID 34321587, 2021). "Taken together, these results suggest that miR-210-3p carried by plasma EVs was increased in CLP-induced sepsis mice and stimulated the lung tissue secretion of inflammatory factors via ATG7 to induce ALI." (PMID 34321587, 2021). "Taken together, the key findings of the current study demonstrate that plasma EVs carrying miR-210-3p target ATG7 to regulate autophagy and inflammatory activation in a sepsis-induced ALI model." (PMID 34321587, 2021). "This study aimed to investigate the role of autophagy in sepsis-induced T cell apoptosis and immunosuppression, using knockout mice with T cell specific deletion of autophagy essential gene Atg7." (PMID 25029098, 2014). "ATG7 knockout mice exhibit more severe mitochondrial dysfunction and muscle atrophy during sepsis." (PMID 39290495, 2024). "In summary, the delivery of miR-210-3p by peripheral circulating EVs may play a role in ALI in the context of sepsis by targeting ATG7." (PMID 34321587, 2021). "Therefore in this study we employed a mouse with Atg7 knockout specific to T lymphocytes only, in order to determine the role of autophagy in regulating T lymphocyte apoptosis and immune responses in sepsis." (PMID 25029098, 2014). "Moreover, we demonstrated that mice lacking the essential autophagy gene Atg7 in T lymphocytes were more susceptible to death after sepsis." (PMID 25029098, 2014).
Sepsis (continued). "Moreover, mice lacking Atg7 in T lymphocytes showed an increase in sepsis-induced mortality, T cell apoptosis and loss of CD4+ and CD8+ T cells, in comparison to control mice." (PMID 25029098, 2014). "In the present study we demonstrated that mice with disruption of Atg7 in T cells exhibited a reduced cytokine production of IL-2, IFN-γ, IL-4, IL-10 and IL-17 by CD4+ T cells after sepsis, compared to septic wild-type mice." (PMID 25029098, 2014). "Sepsis was induced in a cecal ligation and puncture (CLP) model, with T-cell-specific Atg7-knockout mice compared to control mice." (PMID 25029098, 2014). "For example, in the cecal ligation puncture (CLP)–-induced sepsis mice model, the levels of LC3-II, ATG5, and ATG7 are downregulated in the lung of mice with sepsis, suggesting that sepsis may suppress autophagy." (PMID 30717487, 2019). "We further identified the expression levels of LC3-II and ATG7 by lysate proteins extracted from CD4+ and CD8+ T cells at 24 h after CLP, as autophagy detected by Cyto-ID Green/acridine orange staining was inhibited at the late stage of sepsis." (PMID 25029098, 2014). "This study emphasized the upregulation of autophagy-related proteins, such as LC3, Atg7, and Beclin 1, mediated by ghrelin through AMPK-dependent pathways, which also mitigates mitochondrial dysfunction and oxidative stress, key drivers of sepsis-induced organ damage." (PMID 39857660, 2024). "Furthermore, Atg7 expression was not changed by CLP-induced sepsis, while the levels of this protein were increased upon HIPK2 overexpression." (PMID 30154452, 2018). "HIPK2 overexpression increased the level of the Atg7 protein, which was not affected by CLP-induced sepsis, suggesting that HIPK2 overexpression promotes phagophore expansion and increases mature autophagosome formation in sepsis." (PMID 30154452, 2018).